APOE (apolipoprotein E)
Diseases named in the same sentence as APOE in open-access papers (continued):
Sharing a sentence is not in itself a finding about the gene and the disease.
dementia (continued). "Moreover, previous research has shown that lifelong engagement in intellectually stimulating activities, indicative of enhanced cognitive resilience, was able to mitigate the risk of dementia attributable to APOE-ε4 activity, thus enabling better health trajectories even in at-risk subpopulations." (PMID 40341863, 2025). "This could also help build a prognostic model so that the groups characterized by unique cognitive decline patterns can be predicted using the selected corresponding features like participants demographics, APOE genotype, cardiovascular risk factors, and other existing AD or dementia biomarkers." (PMID 40636900, 2025). "Moreover, the APOE ε4 allele, a well-established genetic risk factor for dementia, may synergistically interact with Diabetes." (PMID 40641975, 2025). "Biomarker associations with delirium, and with incident dementia on follow-up, will be determined using logistic or Cox regression as appropriate, unadjusted and adjusted for covariates including demographics, baseline cognition, frailty, comorbidity and apolipoprotein E genotype." (PMID 40514232, 2025). "This may be due to the fact that the magnitude of effect estimates for the risk of developing dementia linked to air pollution are lower than some traditional ones, such as lifestyle choices, socioeconomic status and genetic predisposition (i.e. APOE ɛ4/4 alleles)." (PMID 41194168, 2025). "Caution has been advised in interpreting sex-specific genetic associations, given the differential sex survival distributions and the possibility that the ApoE gene may have pleiotropic effects influencing both the risk of dementia and mortality/longevity which can introduce spurious associations." (PMID 41109864, 2025). "However, before manipulating ApoE levels as a safe therapeutic intervention to prevent or delay AD related dementias, a comprehensive understanding of the prolonged repercussions of ApoE loss of function in critical brain regions, such as the hippocampus, is crucial." (PMID 38891031, 2024). "As currently identified genetic risk factors, including APOE, explain only 30–40% of familial dementia risk, assessment of family history in relation to brain health at younger ages could improve understanding of the timing and nature of hereditary and environmental effects on brain health." (PMID 39387967, 2024). "Thus, plasma NfL and pTau 181, combined with APOE genotype, may help to identify individuals at increased risk of dementia." (PMID 38654932, 2024). "Furthermore, genetic background, such as apolipoprotein E epsilon 4 (APOE4), has been demonstrated to be the important risk factor of dementia; whether there exists the moderation effect remains to be explored." (PMID 38520024, 2024). "Furthermore, APOE-ɛ4 is a strong determinant of dementia and interacts with other risk factors." (PMID 37605096, 2024). "Population studies with follow-ups from 3 to 20 years report that SCCs may predict MCI and/or dementia, usually in combination with other variables such as being a woman or having a high educational level and being a carrier of the APOE e4 gene, causing concern in the patient." (PMID 39727504, 2024). "Recent intervention studies suggesting a role for certain monoclonal antibody derived therapies such as donanemab may provide a stronger rationale for the identification and treatment of individuals found to be at high risk of dementia though high risk APOE genotypes or a very high HDL level." (PMID 38456089, 2024). "APOE‐ε4 status and a family history of dementia were entirely unassociated with neighborhood disadvantage in the cohort—a finding matched in older adult studies, where neighborhood‐dementia association estimates tend to be unchanged by adjustment for genetic risk." (PMID 38482967, 2024).
dementia (continued). "Consuming at least 7 g/d of olive oil was associated with a 28% lower risk of dementia-related death (adjusted pooled HR, 0.72 [95% CI, 0.64-0.81]) compared with never or rarely consuming olive oil (P for trend < .001); results were consistent after further adjustment for APOE ε4." (PMID 38709531, 2024). "Participants who developed dementia during follow‐up showed a risk profile similar to that for people with higher neuroticism levels regarding socioeconomic status and comorbidities but were more likely to be male, APOE ε4 carriers, and have a high non‐APOE PRS (eTable 5)." (PMID 38984680, 2024). "The APOE Ɛ4 haplotype, which is a combination of two missense variants, was first described by the Roses lab at the Duke University Medical Centre as a causal locus for dementia, and has been associated with dementia in populations across the world, though with varying effect sizes." (PMID 38028602, 2023). "In addition, APOE-ε4 also may increase the susceptibility of viral infection and cerebrovascular disease during COVID-19 as well as promote long-term disability with dementia and long-COVID syndrome." (PMID 37238686, 2023). "WMH burden and APOE genotype clarify the relationship between blood pressure and cognitive functions, and may allow for a more accurate assessment of the impact of high blood pressure on cognitive decline and dementia risk." (PMID 37987468, 2023). "With strong support for a direct association between low plasma apoE levels and an increased risk of AD and other types of dementia, we aimed to assess whether the lower ε4-induced risk of AD in B/AAs may be attributed to a different plasma apoE profile than that previously reported in whites." (PMID 37400888, 2023). "Given that risks for dementia and cognitive decline and peripheral biomarker signatures may both be influenced by APOE genotype carrier status, we also examined the association between inflammatory biomarkers and cognitive outcomes in different APOE strata." (PMID 37584418, 2023). "By contrast, for non-APOE4 carriers, the I allele, which increases CETP and decreases HDL, was associated with greater baseline thickness and lower dementia risk, suggesting that APOE genotype may modify the impact of CETP polymorphisms on neurodegeneration and cognitive decline." (PMID 37974180, 2023). "With an emerging interest in the role of the APOE genotype in mediating metformin's effects on cognitive decline in AD patients, we sought to investigate whether metformin usage is associated with a reduced risk of severe dementia." (PMID 38001936, 2023). "Therefore, the already increased dementia risk in APOE ε4 carriers may attenuate the inverse relations between faster walking pace and the risk of dementia." (PMID 36624486, 2023). "In addition, PD patients carrying ApoE ε4 might have a greater risk to develop additional dementia, in comparison to non-ApoE4-carriers." (PMID 36817952, 2023). "Notably, all genes involved in synaptic transmission had more “weight” than polymorphisms in APOE, suggesting that APOE is insufficient as a single genetic predictor of dementia and further highlighting the importance of a polygenic approach to risk assessment." (PMID 37953886, 2023). "While APOE-ε4 is generally thought to be detrimental in urban European contexts due to high blood lipid levels, increased cardiovascular disease risk, and higher rates of dementia, the Tsimane generally have low levels of lipids, cardiovascular disease, and dementia." (PMID 37556539, 2023). "A growing amount of epidemiological evidence suggests that several lifestyle factors (e.g., smoking, physical activity, and fish intake) and environmental factors (e.g., sunlight, greenspace) may interact with APOE alleles to synergistically affect the risk of dementia development." (PMID 37246226, 2023).
dementia (continued). "Overall, these data supported our hypothesis that the APOEε3/ε4 risk genotype confers unique effects compared to APOEε4/ε4 and signify the need to better understand the effect of heterozygous APOE genotypes and how these differences may play a role in risk for dementia." (PMID 35370604, 2022). "Mechanisms underlying potential APOE-diet interactions in relation to dementia risk may involve altered metabolism of n-3 fatty acids, glucose or ketones, impaired transport of fatty acids and cholesterol, or modification of other risk factors where APOE status is involved." (PMID 34632537, 2022). "Existing studies have included Apolipoprotein E (APOE) genotype as the genetic risk, focused on wider psychosocial characteristics, relied on small samples, and provided limited evidence for the interplay of genetic risk and social relations predicting the increased risk of incident dementia." (PMID 35197341, 2022). "Thus, underdiagnosed dementia might contribute to the doubled risk of CDR≥1 among the APOE ε4 carriers' group, as was observed in this study group." (PMID 39081475, 2022). "Therefore, humanized APOE mice have contributed greatly to what we currently understand about the myriad of APOE mechanisms that may contribute risk for dementia." (PMID 35370604, 2022). "Hence, the current study investigates the association between the BIN1 rs744373 SNP and performance across different cognitive domains, and compares these findings with APOE ε4 allele, the most established risk factor for AD, among healthy ageing men free of severe cognitive impairment or dementia." (PMID 36280690, 2022). "Thus, we demonstrated that PPI use and dementia associations might vary across APOE ε4 genotypes for the first time." (PMID 36045363, 2022). "Compared to participants free of dementia, those with incident all-cause dementia had more frequently a lower educational level, diabetes mellitus, cardiovascular disorder, and depressive status and were more likely to be confined at home and carriers of APOE-ε4." (PMID 35057850, 2022). "Hence, these findings could be related to the higher incidence of AD in women and the link between low plasma apoE levels and an increased risk of suffering dementia." (PMID 36153580, 2022). "Thus, we suggest that the combination of MTA and APOE-4 genotype may represent a promising risk factor for the prediction of progression from aMCI to dementia." (PMID 35492717, 2022). "In addition, we may not have been able to detect modification of the associations between EN-RAGE and S-RAGE and dementia by APOE status, owing to small numbers within the strata." (PMID 33416887, 2021). "However, at present whether APOE ε4 allele carriage interacts with lifestyle factors, such as diet, influencing risk of dementia remains unclear." (PMID 33748832, 2021). "For example, a population based study of more than 1,600 older adults assessing the interaction between APOE status and exercise on dementia risk over a 5-year period suggests that physical exercise significantly moderated the relationship between genotype and dementia." (PMID 34276532, 2021). "Finally, we performed additional post hoc analyses to test whether sAD symptomatic individuals (MCI and dementia) had a higher PAD than asymptomatic individuals at risk of sAD (APOE ε4 carriers)." (PMID 34504080, 2021). "In addition, specific combinations of environmental and genetic (APOE, in particular) risk factors may affect the risk of dementia." (PMID 34764935, 2021). "The use of the modeling technique provided allows for direct estimates of the both time to dementia diagnosis and risk of diagnosis within the same model and allows for greater characterization of APOE ε4 allele carrier status on risk of dementia than isolated models may provide." (PMID 34744974, 2021).
dementia (continued). "Inconsistency in these and our study results may reflect particular cohort characteristics; in particular our participants were younger (50–68 y) and this may have led to our insignificant interactions between APOE genotype and meat intake with dementia risk in this population." (PMID 33748832, 2021). "Additionally, most prior studies of APOE ε4 and dementia only estimate risk of dementia." (PMID 34744974, 2021). "Furthermore, some studies on the interaction between APOE ε4 genotype and modifiable risk factors on dementia found significant results, with the effects of these favorable factors being more pronounced among APOE 4 carriers than the non-carriers, which echoes our findings." (PMID 34355006, 2021). "Although risk of dementia is greater in Blacks compared with Whites, the relative effect of APOE ε4 may be greater in Whites compared with Blacks, potentially because a larger component of the risk seen in Blacks is due to other health factors such as vascular disease." (PMID 34744974, 2021). "Epidemiological evidence allows to estimate that 40% of dementia cases are due to lifestyle and cardiovascular modifiable risk factors, while the remaining cases are largely explained by genetic (e.g., APOE ɛ4), biological (e.g., amyloid and tau), other unknown risk factors, and their interactions." (PMID 34635163, 2021). "In addition, it has been hypothesized that the apolipoprotein ε4 (APOE-ε4) allele is the major genetic risk factor for the most common form of dementia; AD dementia has an influence on lipid homeostasis deregulation." (PMID 33573174, 2021). "However, we found that the APOE ɛ4 allele predicted dementia in the low‐risk AD‐PRSs tertile." (PMID 33532541, 2021). "ApoE ε4 appears to be a risk factor common to both AD and COVID-19-related outcomes, since symptom severity and mortality rates have been found to be significantly worse in ε4 homozygotes, independently of any common comorbidities (i.e., coronary heart disease, dementia, diabetes, and hypertension)." (PMID 34149394, 2021). "Whether there is a relationship between the risk for regression and the later risk of dementia is unknown and specifically whether there are genetic markers that affect the vulnerability to dementia (e.g., ApoE genotype and soluble TREM-2) are also associated with regression." (PMID 34573218, 2021). "In addition, this classification might give useful insights for better addressing the therapeutic strategies, since multiple studies over the past two decades have demonstrated that APOE variants may affect the therapeutic response to anti-dementia drugs." (PMID 32694537, 2020). "AD prevalence increases exponentially as age increases, so dementia factors have a high age distribution, while the controls belong to a lower age group that is not yet at risk of dementia, so it may seem that the control groups have lower APOE e4 prevalence." (PMID 32770103, 2020). "It is also possible that such APOE targeted therapies could help with co-morbidities associated with dementia or aging, such as diabetes and cardiovascular disease for E4 carriers, vascular dementia for E4 carriers, neuroinflammation for E4 carriers and type III hyperlipoproteinemia for E2 carriers." (PMID 32005122, 2020). "Therefore, APOE ε4 carriers with SCD have an additional risk for dementia." (PMID 32671080, 2020). "In conclusion, after over an average of 7 years’ follow-up, our findings indicate that the combination of telmisartan and rosuvastatin might be an effective prevention and/or treatment strategy for cognitive impairment and dementia in hypertensive patients, especially in those with APOE ε4 allele." (PMID 32581766, 2020). "Older age and the apolipoprotein e4 (APOE4) genotype are the leading constitutional risk factors for AD, yet modifiable vascular-related risk factors are associated with additional late-life risk of AD, dementia risk and AD pathology biomarkers in preclinical older-age individuals." (PMID 33168064, 2020).
dementia (continued). "While some midlife lifestyle/vascular risk factors have been reported to have a more pronounced detrimental impact on dementia risk among APOE ε4 carriers compared with non‐carriers, it is possible that the impact of such risk factors among carriers may become less pronounced at older ages." (PMID 31736136, 2020). "In addition to age, the presence of the e4 allele of the apolipoprotein E (APOE) gene increases the risk of dementia, and may strengthen the effect of other risk factors." (PMID 32276604, 2020). "The APOE-ε4 allele and eating behavior might modify lipid metabolism in dementia." (PMID 33312717, 2020). "Thus, the risks of dementia might be reduced by rosuvastain in subjects with APOE ε4 allele that has been regarded as a statin treatment threshold in clinical practice." (PMID 32581766, 2020). "Interestingly, the highest level significantly correlated with all causes of dementia, and especially of VaD, even after adjusting for age, gender, apolipoprotein E4 (APOE4), education, body mass index, MMSE, hypertension, cerebrovascular events, and estimated glomerular filtration rate." (PMID 32340195, 2020). "Therefore, this study investigated the association between cognitive performance and both BG and the lipid profile in APOE ε3/ε3 genotype carriers, as compared to that in APOE ε4 or APOE ε2 allele carriers, in dementia-free, community-dwelling older Chinese Han adults." (PMID 30984391, 2019). "In addition to methodological differences, other factors may contribute to discrepancies between study results on plasma amyloid and tau levels, including age, APOE allele status, duration of dementia, and other genetic risk factors." (PMID 31389176, 2019). "Thus, APOE ε4 allele is associated primarily with cognitive decline owing to incipient dementia." (PMID 31214016, 2019). "The current study examined for the first time whether an environmental factor that is assimilated from the surrounding culture, positive age beliefs—or perceptions about various aspects of old age, reduces the risk of dementia for APOE ε4 carriers as well as older individuals in general." (PMID 29414991, 2018). "Controlling for APOE genotype in addition to age, education, household assets, marital status, hazardous alcohol use, stroke and height did not affect the fully adjusted association between reproductive period and incident dementia (ASHR 1.018, 95% CI 0.998–1.038, I2 = 0.0%)." (PMID 29489847, 2018). "Finally, we test the hypothesis that APOE genotype modifies any effect of reproductive period on incident dementia risk." (PMID 29489847, 2018). "Fourth, ApoE genotype might alter the association between use of statins and incidence of dementia." (PMID 29643479, 2018). "By contrast, patient H was homozygous for APOE ε4 allele, had a family history for dementia (4 brothers) and plausibly the combination of these risk factors, likely coupled with a pre-existent cerebrovascular disorder, may explain the earlier age at onset compared to the other patients (64 years)." (PMID 29544907, 2018). "Finally, we note that the APOE genotype was known only in participants who survived until 2000, which may have biased the associations between fasting insulin, genotype, and dementia." (PMID 29997193, 2018). "In addition, both cognition and APOE ε4 genotype may influence the association between Aβ and gait speed in dementia-free older adults." (PMID 29987248, 2018). "If so, then APOE may exert a life-long influence over δ and therefore all-cause dementia risk." (PMID 28291794, 2017). "Recent literature suggest that ApoE polymorphism may alter the risk of dementia in PD patients." (PMID 29326545, 2017). "Thus, Aβ deposition in the DMN might mediate APOE’s association with dementia, and that association may manifest as a disruption of intelligence, not domain-specific cognitive performance." (PMID 28291794, 2017).